FRMPD4 (FERM and PDZ domain containing 4)
Description:
Positive regulator of dendritic spine morphogenesis and density. Required for the maintenance of excitatory synaptic transmission. Binds phosphatidylinositol 4,5-bisphosphate.
Synonyms: KIAA0316; PDZD10; PDZK10; MRX104; XLID104
Tractability: PROTAC: ubiquitination databases record sites on it.
Gene: Protein-coding gene on chromosome X (11,822,423 to 12,724,523, forward strand). Ensembl gene ENSG00000169933.
Subcellular location: Cell projection, dendritic spine
Gene Ontology:
Molecular function: phosphatidylinositol-4,5-bisphosphate binding; protein binding
Biological process: positive regulation of synapse structural plasticity
Cellular component: dendritic spine; protein-containing complex; postsynapse
Gene-disease validity (ClinGen):
ClinGen rates the evidence that FRMPD4 causes each of these diseases.
X-linked complex neurodevelopmental disorder (X-linked): Definitive. A complex neurodevelopmental disorder that is transmitted via X-linked inheritance, and is characterized by intellectual disability, autism and epilepsy.
Homologues: Orthologues: dog FRMPD4 (93% identical), pig FRMPD4 (91% identical), rat Frmpd4 (90% identical), mouse Frmpd4 (89% identical), chimpanzee FRMPD4 (74% identical), macaque FRMPD4 (74% identical), guinea pig FRMPD4 (69% identical), tropical clawed frog frmpd4 (64% identical), rabbit FRMPD4 (58% identical), zebrafish frmpd4 (41% identical), Drosophila melanogaster CG42788 (20% identical), Caenorhabditis elegans frm-8 (13% identical). Paralogues in human: FRMPD3 (30% identical), FRMPD1 (23% identical).
Diseases named in the same sentence as FRMPD4 in open-access papers:
FRMPD4 is named in the same sentence as 12 diseases in open-access papers, as found by Europe PMC text mining. Sharing a sentence is not in itself a finding about the gene and the disease. The quoted sentences say what the papers report.
autism (4 papers, 2015 to 2025). Persistent deficits in social interaction and communication and interaction as well as a markedly restricted repertoire of activity and interest as well as repetitive patterns of behavior. "Several genes were also found to be rarely associated with autism in literature databases such as FRMPD4." (PMID 40642607, 2025). "Hub genes of the turquoise module included one GABA receptor encoding genes such as Gabrb1, one glutamate receptor gene (Grid2) and genes tightly associated with synaptic development and autism (Nrxn1, Lrfn5, Plcb1, Erc2, Frmpd4, Tanc2, Ctnnd2, Dmd)." (PMID 34021132, 2021). "FRMPD4, which has been associated with autism and schizophrenia, encodes a product that regulates dendritic spine morphogenesis." (PMID 25888122, 2015).
Intellectual disability (4 papers, 2015 to 2026). "FRMPD4 is an X-linked intellectual disability gene and is associated with low educational attainment." (PMID 39633006, 2025). "Furthermore, mutations in FRMPD4, resulting in significant protein loss, have been linked to a severe form of intellectual disability." (PMID 36309735, 2022). "On the other hand, the variant in FRMPD4 might modify the genetic background and thereby contribute to the intellectual disability of the propositi." (PMID 25888122, 2015). "FRMPD4 (FERM and PDZ Domain Containing 4) has previously been associated with intellectual disability and epilepsy." (PMID 41959831, 2026).
schizophrenia (3 papers, 2015 to 2022). A major psychotic disorder characterized by abnormalities in the perception or expression of reality. "Polymorphisms in human FRMPD4 have been previously linked to sex differences in schizophrenia and mutations in FRMPD4 can cause an X-linked intellectual disability." (PMID 35228715, 2022).
Amyloid (1 paper, 2025). "Amyloid plaque burden was found to be significantly associated (P < 4.39 × 10−4) with methylation changes in FRMPD4, ARHGAP6 (in the FRMPD4 locus), and DMD." (PMID 39633006, 2025).
cognitive decline (1 paper, 2025). "The association of the index variant of the FRMPD4 locus with cognitive decline could thus be linked to a lower cognitive reserve." (PMID 39633006, 2025).
emphysema (1 paper, 2023). "In the emphysema XWAS, the top suggestive association in all subjects was a variant in FRMPD4, located 332 kb upstream of the TMSB4X variant in the Xp22.2 locus; both FRMPD4 and TMSB4X escape XCI." (PMID 36726148, 2023).
genetic diseases (1 paper, 2017). "WES enabled timely diagnosing of genetic diseases, validation of causality of specific genetic disorders of PTPN23, KCTD3, SCN3A, PPOX, FRMPD4, and SCN1B, and setting dual diagnoses by detecting two causative variants in distinct genes in the same patient." (PMID 27848944, 2017).
FRMPD4 also shares sentences with these, for which no sentence is quoted: epilepsy (2 papers); hearing loss (1); neurodevelopmental disorder (1); sensorineural hearing loss (1); X-linked intellectual disability (1).